FOXO1 (forkhead box O1)
Diseases named in the same sentence as FOXO1 in open-access papers (continued):
Sharing a sentence is not in itself a finding about the gene and the disease.
asthma (11 papers, 2016 to 2025). "Corroborating in vitro data, in vivo blockade of Foxo1 resulted in reduced signs of asthma as measured by AHR and associated with reduced frequency of IL-9+CD4+T cells in the lungs." (PMID 29867972, 2018). "Treg cells that lack FoxO1 upregulate expression of the pro-inflammatory cytokine interferon γ (IFNγ), the production of which is linked to severe, glucocorticoid-resistant asthma in humans." (PMID 28267764, 2017). "Since our in vitro data suggests a strong association of IL-9 and Foxo1, hence we speculated if Foxo1 also regulates IL-9 in vivo during the pathogenesis of asthma." (PMID 29867972, 2018). "Furthermore, loss of Foxo1 attenuates IL-9 in mouse and human Th9 and Th17 cells, and ameliorates allergic inflammation in asthma." (PMID 28993609, 2017). "Furthermore, loss of Foxo1 suppresses IL-9 production in mouse and human Th9 and Th17 cells and substantially ameliorates allergic inflammation in asthma." (PMID 28993609, 2017). "Compatible results of another study reported that gene expression of FoxO1 was overexpressed in pulmonary macrophages in patients who were exposed to house dust mite allergens and had mild asthma." (PMID 37987301, 2023). "Our present study provides strong evidence demonstrating that Foxo1-IL-9 axis plays a crucial role in the regulation of adaptive immune response in asthma-like mouse models." (PMID 29339772, 2018). "Lastly, adoptive transfer of Th9 cells into lungs induced asthma-like symptoms that were ameliorated by Foxo1 inhibitor, AS1842856." (PMID 29339772, 2018). "Inhibition of Foxo1 has double impact on both adaptive and innate immune responses in experimental asthma with promising implications in asthmatic patients." (PMID 29339772, 2018). "Our data demonstrated therapeutic efficacy of Foxo1-siRNA and Foxo1 inhibitor in inhibiting IL-9 and ameliorating signs of ova-induced asthma in mice." (PMID 28993609, 2017). "To avoid the interference of pre-activated T cells in asthma model, we used therapeutic approach to knock-down Foxo1 using siRNA in asthma model." (PMID 28993609, 2017). "Inhibition of Foxo1 not only suppressed IL-9 induction IL-9-producing T cells but also ameliorated development of asthma." (PMID 28993609, 2017). "Furthermore, elevated FoxO1 expression in airway macrophages among patients with mild asthma induces macrophage polarization in the lungs, which is involved in airway inflammation and airway remodeling in asthma." (PMID 37259023, 2023). "In this study, we examined the role of miRNA in targeting FOXO1 in asthma." (PMID 36253857, 2022). "Moreover, a significant changes of several cytokines related to Th9 cell differentiation in mouse asthma model was detected compared with the control mice group, including forkhead box O1(FOXO1), IL-4, IL-9, IRF4, Spi1, BATF, and IRF1." (PMID 36253857, 2022). "Our results demonstrated that the DC-derived exosomes can inhibit Th9 cell differentiation through miR-493-5p, thus DC-derived exosomal miR-493-5p/FOXO1/Th9 may serve as a potential therapeutic target in the development of asthma." (PMID 36253857, 2022). "Finally, Foxo1 inhibitor ameliorates asthma-like symptoms induced by adoptive transfer of Ova-specific Th9 cells in mice." (PMID 29339772, 2018). "Together, targeting Foxo1 may have dual impact on the immune responses in asthma by regulating both innate and adaptive immune responses thus ameliorating the disease symptoms." (PMID 29339772, 2018). "Since Foxo1 inhibition in asthma model reduced IL-9-dependent inflammation and antitumor potential of Th9 cells, hence targeting Foxo1 could provide a potential therapeutic advantage in these diseases." (PMID 29867972, 2018). "The role of Foxo1 in the regulating innate immune response in asthma has been recently described." (PMID 29339772, 2018).
asthma (continued). "Because of these defects and activated phenotypes of T cells in Foxo1-CD4-conditional deficient mice, we have used alternate approach to therapeutically block Foxo1 using Foxo1-siRNA or Foxo1-chemical inhibitor in experimental allergic inflammation model of asthma." (PMID 28993609, 2017). "Similarly, Foxo1-inhibitor attenuated Ova-induced asthma (unpublished observations), IL-9 induction and PAS-positive goblet cells." (PMID 28993609, 2017). "Foxo1 inhibitor reduced the total cell counts, eosinophil and T-cell number in asthma model." (PMID 28993609, 2017). "Consequently, inhibition of Foxo1 ameliorated the disease in an asthma-like mouse model." (PMID 29339772, 2018). "Interestingly, the phosphatase PP2A has been shown to dephosphorylate FoxO1 in certain cell types, and patients with severe glucocorticoid-resistant asthma exhibit decreased expression of the serine-threonine phosphatase PP2A in their peripheral blood monocytes." (PMID 28267764, 2017). "The roles of SIRT1 and FoxO1 and their interactions in different types of diseases such as tumor progression, toxoplasmosis, and asthma are not completely elucidated." (PMID 37987301, 2023). "Without manipulation of FoxO1 function, this approach that we chose for our study allow us to focus our intervention strategy for treating asthma through regulation of type 2 immune response via FoxO1-IRF4 signaling pathway." (PMID 27007158, 2016). "However, to date, Foxo1 was not involved in the regulation of inflammatory T cells in asthma experimental models and particularly Th9 cells." (PMID 29339772, 2018).
Atrophy (11 papers, 2012 to 2025). Any weakening or degeneration, especially through lack of use. "In particular, Epicatechin, a flavanol found in tea and other consumable plants, has also been demonstrated to enhance muscular function in some atrophy models by inhibiting FOXO1, Atrogin1, and MuRF1." (PMID 36618945, 2022). "FOXO1 is regarded as an atrophy gene and acts as a sensor to induce muscle atrophy (McLoughlinet al, 2009)." (PMID 27007909, 2016). "Though FoxO-1 is related to lysosomal atrophy, the mRNA level of cathepsin-L only slightly increased in our experiment." (PMID 25797259, 2015). "Altogether, these studies highly suggest that both FoxO1 and FoxO3a are potent inducers of MuRF1 in several atrophy models, but that their implication may be highly dependent on the model used and synergized by other transcription factors." (PMID 32933049, 2020). "FoxO1 and 3a were also proposed to be important drivers of cardiac atrophy upon sympathetic denervation although direct effect was not addressed (Giulia, Circ Res, 2013)." (PMID 32933049, 2020).
cardiomyopathy (11 papers, 2014 to 2026). A disease of the heart muscle or myocardium proper. "Some studies have reported diverse roles of FoxO1 in septic organ injury, including downregulation of nuclear FoxO1 in cardiomyopathy, upregulation of FoxO1 in pulmonary endothelial injury, and decreased of FoxO1 acetylation in kidney injury 18-20." (PMID 41362741, 2026). "In turn, PPARα prompts the nuclear translocation of the forkhead box O1 (FOXO1) transcription factor, promoting the progression of cardiomyopathy." (PMID 38994977, 2024). "FOXO1 knock-down was shown to be protective in a model of diet-induced cardiomyopathy." (PMID 30420836, 2018). "FoxO1 function has been investigated in the tissues and cells of various genetically modified mice of different disease models such as diabetic complications, cardiomyopathy, carcinogenesis, innate immune response, and adaptive immunity." (PMID 27007158, 2016). "Several reports confirm that FOXO1 plays both a positive and negative role in autophagy related cardiomyopathy." (PMID 24864265, 2014).
chronic myeloid leukemia (11 papers, 2005 to 2025). "In Chronic myeloid leukemia, FOXO1 is upregulated in drug-resistant cells with BCR-ABL1 kinase mutation." (PMID 37065484, 2023). "In chronic myelogenous leukemia, a tyrosine kinase inhibitor (imatinib) activated FOXO1 and FOXO3 by blocking the PI3K-AKT pathway, and in turn induced cell-cycle arrest and apoptosis." (PMID 28938528, 2017). "In addition, FOXO1 also inhibits the proliferation and growth of cancer cells in chronic myeloid leukemia (CML) and chronic lymphocytic leukemia (CLL), thereby exerting antitumor effects in hematological tumors." (PMID 36290822, 2022). "PTEN and FOXO1 were previously reported to be the target of miR-486-5p in neonatal rat cardiomyocytes, chronic antibody-mediated rejection in kidney transplantation and chronic myeloid leukemia, together or singlarly." (PMID 29069829, 2017). "SIRT1 effects on forkhead box protein O1 (FOXO1), signal transducer and activator of transcription 5 (STAT5)—related pathways, and tyrosine kinases like BCR-ABL, promoting leukemogenesis in chronic myeloid leukemia (CML), have also been described." (PMID 40149343, 2025). "In vivo and in vitro models show that increased expression of miR-486-5p stimulates differentiation and survival of normal CD34(+) erythroid cells by targeting FOXO1 and PTEN genes, significant up-regulation has been observed in chronic myeloid leukemia (CML)." (PMID 38731114, 2024). "For instance, miR-486-5p is overexpressed in chronic myeloid leukemia and can enhance cell growth via regulation of AKT signaling and FOXO1 expression." (PMID 31762811, 2019).
injury (11 papers, 2015 to 2026). Damage inflicted on the body as the direct or indirect result of an external force, with or without disruption of structural continuity. "Further evidence was provided by in vivo study, which showed that disruption of Gli1 reversed myeloid Foxo1 deficiency-mediated cytoprotection, evidenced by augmented IR-induced liver injury and enhanced NEK7/NLRP3 activity." (PMID 33288903, 2021). "The Forkhead box protein O1(FOXO1)- TfR mechanism leads to ferroptosis in neutrophils with high FOXO1 expression following traumatic brain injury." (PMID 41326356, 2025). "Inhibition of FOXO1, NLRP3, HSP90, or STAT3 has been reported to promote functional recovery after brain injury." (PMID 39310540, 2024). "Our study supports a molecular mechanism by which disruption of PTEN/Foxo1 signaling regulates TLR4-mediated innate immunity, a novel approach for the management of innate immunity-driven lung injury." (PMID 25759027, 2015).
nonalcoholic fatty liver disease (11 papers, 2018 to 2025). "Functional enrichment analysis demonstrated that DEGs of FOXO1 overexpression compared with control were associated with non-alcoholic fatty liver disease, FoxO signaling pathway, cell cycle, and autophagy pathways, closely related to the occurrence and development of HCC." (PMID 35805200, 2022).
breast tumors (10 papers, 2017 to 2024). "However, FOXO1 and 3 have also been implicated in the promotion of breast tumour cell invasion." (PMID 29484124, 2018). "Concomitant reduction of mRNA expression levels of FOXO1 with HBP1 were also observed in a set of breast tumors." (PMID 28099936, 2017). "We demonstrated that cancer stemness as represented by FOXO1 over-expression could characterize breast tumors likely to positively respond to CAP treatment." (PMID 35637961, 2022). "In addition, miR-223 was demonstrated to function as a potential tumor marker for breast neoplasm through suppressing its protein expression of FOXO1." (PMID 34447416, 2021). "Low expression of FOXO1 or FOXO3 protein in breast tumors is correlated with poor clinical outcome." (PMID 32332845, 2020). "Notably, FOXO1 and FOXO3 proteins have been implicated in the promotion of breast tumor cell invasion." (PMID 32332845, 2020). "Consequently, the ratio between active (unphosphorylated) FOXO1 and inactive pFOXO1 was increased in breast tumor cells after treatment with SB-699551." (PMID 32758183, 2020). "We chose AKT 1/2 inhibitor as AKT inhibitor (AKTi) and confirmed its effects by examining phosphorylation statuses of AKT at S473 and its downstream FOXO1 at T24 in cultured HUVECs and ECs of MMTV-PyMT spontaneous breast tumour." (PMID 34285232, 2021). "The RPPA method demonstrated a wide range of FOXO1 protein expression (ranging from 0.07 to 1.91) and FOXO3 protein expression (ranging from 0.19 to 3.98) in breast tumors." (PMID 32332845, 2020). "To investigate the role of FOXO1 and FOXO3 genes in breast carcinogenesis, we therefore used the RPPA method to perform a comparative study of the protein expression of these two FOXO genes in a series of 218 breast tumors." (PMID 32332845, 2020). "To better define the role of FOXO1 and FOXO3 transcriptional factors in breast carcinogenesis, we performed a comparative study of their expression at both the RNA and protein levels in a series of human breast tumors." (PMID 32332845, 2020). "Finally, Pep2–Ae enhanced the activity of AKT1 and FOXO1, and reduced the expression of FOXO1 and SOX2 in MMTV-PyMT MEC-derived breast tumors and PDX-derived breast tumors." (PMID 31844113, 2019). "We confirmed that FOXO6, but not FOXO1, 3 or 4, was frequently overexpressed in breast cell lines (25%) and in breast tumours (26.9%)." (PMID 29484124, 2018). "Therefore, our results suggest that high activity of the PI3K/AKT/mTOR pathway in breast tumors would induce degradation of FOXO3 protein, but not FOXO1 protein." (PMID 32332845, 2020).
Burkitt lymphoma (10 papers, 2019 to 2025). A rare form of malignant mature B-cell non-Hodgkin lymphoma. "Approximately 10% of DLBCL and Burkitt lymphomas carry FoxO1 mutations that lead to FoxO1 retention in the nucleus (specifically T24 mutation) and its increased transcriptional activity." (PMID 39436708, 2024). "In Burkitt lymphoma, mantle cell lymphoma, follicular lymphoma, and chronic lymphocytic leukemia or acute lymphoblastic leukemia, FoxO1 exhibits a key oncogenic character that allows cell survival, suggesting the possibility of its therapeutic targeting." (PMID 39533662, 2025). "On the other hand, FoxO1's ‘oncogenic’ character has been described in Burkitt lymphoma, mantle cell lymphoma, or chronic lymphocytic leukemia, with malignant B cells utilizing FoxO1 to increase their fitness." (PMID 39533662, 2025). "It is reported that FOXO1 confers long-term maintenance of the dark zone proliferation program and can acted as a pharmacologically target in adult Burkitt Lymphoma." (PMID 36292640, 2022). "It was shown the abundant nuclear localization of FOXO1 in Burkitt’s lymphoma (BL)." (PMID 32549409, 2020). "The quinoline-based forkhead box protein O1 (FOXO1) inhibitor AS1842856 blocked cell growth, induced apoptosis, and suppressed MYB by upregulation of the tumor suppressor miR-150 in BL-41 and Namalwa Burkitt lymphoma cells." (PMID 38835346, 2024).
chronic kidney disease (10 papers, 2017 to 2025). Impairment of the renal function secondary to chronic kidney damage persisting for three or more months. "Overexpression of miR-27a in mice with chronic kidney disease attenuated muscle loss, improved grip strength and reduced the expression of FoxO1, MuRF1and Atrogin140." (PMID 34193880, 2021). "Although the miR-27a-–FoxO1 interaction is not validated in skeletal muscle cells, the overexpression of miR-27a in mice with chronic kidney disease attenuated muscle loss, improved grip strength, and decreased the expression of FoxO1, Trim63, and Fbxo32 proteins." (PMID 31013615, 2019). "Fork_head family include FoxO1, which conformed to regulate E3 ligase then leads to muscle wasting in chronic kidney disease." (PMID 40034749, 2025). "A single study highlighted that exo-miRNA-26a, containing muscle surface peptides, attenuated cardiac fibrosis and improved cardiac function through mediating forkhead box O1 (FOXO1) downregulation in chronic kidney disease (CKD) mice." (PMID 40386050, 2025). "Under pathological conditions, miR-27a alleviates muscle atrophy in chronic kidney disease or exercise intervention through the Akt/FoxO1 signaling pathway." (PMID 40504789, 2025). "They identified hispaglabridin B (HB) as a possible inhibitor of FoxO1 which was useful for preventing muscle wasting in chronic kidney disease." (PMID 33499405, 2021). "This is well exemplified by direct regulation of PTEN and FOXO1 by miR-486-5p in polycystic ovary syndrome, sebaceous carcinoma and chronic kidney disease." (PMID 29069829, 2017).